PANDAR (promoter of CDKN1A antisense DNA damage activated RNA)
Diseases named in the same sentence as PANDAR in open-access papers (continued):
Sharing a sentence is not in itself a finding about the gene and the disease.
tumor (29 papers, 2014 to 2025). "Further studies found PANDAR involved in autophagic regulation at the levels of transcription and translation, which led to the loss of the survival advantage of tumor cells, thus inhibited cell growth and proliferation." (PMID 32626525, 2020). "The expression of PANDAR was closely associated with tumour size, TNM classification and N classification." (PMID 29416011, 2018). "A clinical pathology characteristic correlation analysis revealed that the upregulated PANDAR was associated with a statistically significant increased tumour size, TNM classification, N classification and a poor survival rate in GC patients." (PMID 29416011, 2018). "In conclusion, we have demonstrated that lncRNA PANDAR is upregulated in ccRCC tissues and is significantly associated with advanced tumor progression." (PMID 28545465, 2017). "PANDAR up regulation was also positively correlated with depth of invasion, tumor size, tumor stage, histological differentiation, and lymph node metastasis." (PMID 35144601, 2022). "In an ovarian tumor xenograft mouse model, the knockdown of CCAT1 reduced tumor weight, whereas PANDAR overexpression increased tumor volume." (PMID 34660304, 2021). "ROC curves identified that the PANDAR levels were a marker for discriminating the early-stage tumour group from the healthy group, the metastasis group from the non-metastasis group and the chemoresistance group from the chemosensitive group in GC patients." (PMID 29416011, 2018). "Compared with the normal samples, the upregulation of PANDAR was identified by a northern blotting analysis in the paired tumour tissues." (PMID 29416011, 2018). "To substantiate the role of PANDAR in tumor growth and cisplatin resistance in addition to in vitro, we created mouse xenograft models via subcutaneous injections of HO-8910PM-Vector-GFP and HO-8910PM-PANDAR-GFP cells, A2780-ctrl shRNA and -shPANDAR cells." (PMID 30375398, 2018). "In vitro and in vivo, PANDAR overexpression improved cell survival rate and tumor growth in response to cisplatin, while depletion of PANDAR leads to a reduced tumor growth." (PMID 30375398, 2018). "Overexpression of PANDAR has been observed in several tumor species and correlated with a poor prognosis for patient survival rate." (PMID 29434205, 2018). "Upregulated PANDAR in GC patients was positively correlated with increased tumour size, advanced TNM classification and a poor survival rate in GC patients." (PMID 29416011, 2018). "The expression of PANDAR was significantly upregulated in tumor tissues when compared with pair-matched normal tissues (P < 0.001)." (PMID 28545465, 2017). "We also observed that MMP-2 and TIMP-3 were downregulated after the knockdown of PANDAR, and MMP-2 and TIMP-3 have been implicated in the regulation of the metabolism of the extracellular matrix, tumor progression and metastasis." (PMID 28545465, 2017). "PANDAR expression was significantly upregulated in tumor tissues and cell lines compared with normal counterparts." (PMID 28545465, 2017). "Our findings provide a potential novel mechanism through which PANDAR boosts tumor cell proliferation, partly due to the up-regulation of p16INK4A through Bmi1." (PMID 26927017, 2016). "Our data suggest that PANDAR was a powerful tumor biomarker, which highlighted its potential clinical utility as a promising prognostic biomarker and therapeutic target." (PMID 27206339, 2016). "We then examined the functional contribution of PANDAR to tumor-like characteristics such as proliferation and apoptosis." (PMID 26927017, 2016). "Our findings provide a novel potential mechanism through which Bcl-2 boosts tumor cell proliferation in part due to the downregulation of lncRNA PANDAR, which releases the NF-YA." (PMID 25719249, 2015).
tumor (continued). "In the present study, we found that lncRNA PANDAR was significantly downregulated in NSCLC tissues than that in corresponding non-tumor lung tissues." (PMID 25719249, 2015). "In a cohort of 140 NSCLC patients, decreased PANDAR expression was negatively correlated with greater tumor size (P<0.001) and advanced TNM stage (P=0.002)." (PMID 25719249, 2015). "Moreover, overexpression of lncRNA PANDAR elevated the tumor growth and cell survival after cisplatin treatment, whereas downregulation of lncRNA PANDAR retarded tumor growth." (PMID 36105363, 2022). "Tumour volume and tumour weight were significantly increased when PANDAR was overexpressed." (PMID 34476001, 2021). "Therefore, we infer that PANDAR regulates KLK4 through miR-367 to affect tumour apoptosis and metastasis." (PMID 34476001, 2021). "The PANDAR more likely functions as a novel tumor suppressor." (PMID 32626525, 2020). "Our results indicate that PANDAR could function as a tumor-promoting gene by regulating the G1/S transition and by promoting tumor invasion." (PMID 28545465, 2017). "Besides, we showed that decreased PANDAR expression was negatively correlated with greater tumor size and advanced TNM stage." (PMID 25719249, 2015). "QRT-PCR analysis was used to detect the average expression of PANDAR in tumor tissues." (PMID 25719249, 2015). "We found that in the tumor tissues as well, CHRF levels were the most up-regulated, compared to UCA1 and PANDAR." (PMID 32901049, 2020). "PANDAR, promoter of CDKN1A antisense DNA damage activated RNA, had significantly upregulated expression in tumor tissues and could serve as an independent predictor of overall survival in ccRCC." (PMID 36530957, 2022). "Additionally, the knockout of PANDAR combined with nutlin-3 reduced the tumour weight of the mice compared with the negative control-treated group." (PMID 29416011, 2018). "In addition, PANDAR was highly expressed in hepatocellular carcinoma tissues and cell lines, and its level was positively correlated with liver cirrhosis, hepatitis B surface antigen (HBsAg), alpha-fetoprotein (AFP), tumor nodule formation, vascular infiltration and TNM staging." (PMID 40713854, 2025).
infection (1 paper, 2021). The state of being infected such as from the introduction of a foreign agent such as serum, vaccine, antigenic substance or organism. "By contrast, PANDAR was overexpressed in MCF-7 cells through lentiviral infection, followed by the CCK8 assay to quantify cell proliferation." (PMID 37551364, 2021).
PANDAR also shares sentences with these, for which no sentence is quoted: hepatocellular carcinoma (6 papers); osteosarcoma (3); cholangiocarcinoma (2); benign renal tumors (1); breast cyst (1); cervical cancer (1); diabetic nephropathy (1); hematological malignancies (1); hematological neoplasms (1); liver cancer (1); liver fibrosis (1); myeloid leukemia (1); myocardial infarction (1); Obesity (1); Oral Squamous Cell Carcinoma (1); pancreatic ductal adenocarcinoma (1); panic disorder (1); perinatal asphyxia (1); retinoblastoma (1); thyroid (1); type 2 diabetes (1).